ENSG00000275915
Gene: Miscellaneous RNA gene on chromosome 1 (11,847,442 to 11,847,549, forward strand). Ensembl gene ENSG00000275915.
Gene Ontology:
Molecular function: mRNA binding
Biological process: regulation of gene expression